BORA (BORA aurora kinase A activator)
Description:
Required for the activation of AURKA at the onset of mitosis.
Synonyms: C13orf34; FLJ22624
Tractability: PROTAC: ubiquitination databases record sites on it.
Gene: Protein-coding gene on chromosome 13 (72,727,749 to 72,756,198, forward strand). Ensembl gene ENSG00000136122.
Subcellular location (Human Protein Atlas): Nucleoli fibrillar center; Nucleoplasm; Cytosol
Pathways (Reactome):
Cell Cycle: Cyclin A/B1/B2 associated events during G2/M transition; Regulation of PLK1 Activity at G2/M Transition
Gene Ontology:
Molecular function: protein binding; protein kinase binding
Biological process: regulation of mitotic nuclear division; regulation of mitotic spindle organization; regulation of protein localization
Cellular component: cytoplasm; cytosol; nucleus; meiotic spindle
Genetic constraint (gnomAD): Loss-of-function variants: 17 observed, 33.58 expected, observed/expected ratio (o/e) 0.51, 90% interval 0.34 to 0.76. The upper end of that interval is the gene's LOEUF score, 0.76, which puts it in group 3 of 6, group 1 being the genes least tolerant of losing a copy. Missense variants: 458 observed, 565.97 expected, observed/expected ratio (o/e) 0.81, 90% interval 0.75 to 0.87. Synonymous variants: 162 observed, 188.03 expected, observed/expected ratio (o/e) 0.86, 90% interval 0.76 to 0.98.
Homologues: Orthologues: chimpanzee BORA (99% identical), macaque BORA (96% identical), pig BORA (83% identical), rabbit BORA (83% identical), dog BORA (79% identical), guinea pig BORA (78% identical), rat Bora (72% identical), mouse Bora (67% identical), tropical clawed frog bora (53% identical), zebrafish bora (39% identical), Drosophila melanogaster bora (21% identical), Caenorhabditis elegans spat-1 (17% identical).
Diseases named in the same sentence as BORA in open-access papers:
BORA is named in the same sentence as 11 diseases in open-access papers, as found by Europe PMC text mining. Sharing a sentence is not in itself a finding about the gene and the disease. The quoted sentences say what the papers report.
bladder cancer (2 papers, 2020). "Our results indicated that BORA was upregulated in human bladder cancer (BCa) compared to the normal bladder and paracancerous tissues at transcriptional and translational levels." (PMID 32655322, 2020). "The function of BORA in cancer was seldomly researched especially in bladder cancer." (PMID 32655322, 2020).
ovarian carcinoma (2 papers, 2020 to 2025). A malignant neoplasm originating from the surface ovarian epithelium. "We are pleased to present our latest findings, which demonstrate that BORA plays a key role in the metastatic capacity of ovarian cancer (OC) cells by triggering a PLK1‐mediated induction of epithelial‐mesenchymal transition (EMT)." (PMID 40151910, 2025). "Altogether, our findings uncovered for the first time a critical role of BORA in the viability of human cancer cells providing potential novel therapeutic opportunities for ovarian cancer management." (PMID 32268485, 2020). "Here we show that Aurora Borealis (BORA), a mitotic protein that plays a key role in activating the master mitotic kinase polo-like kinase 1 (PLK1), has an oncogenic role in ovarian cancer." (PMID 32268485, 2020).
breast tumors (1 paper, 2015). "Firstly, the DIS3/BORA SAGP is significant and synergistic in terms of patients survival in two independent BC patients cohorts; both gene partners are significantly correlated and activated in basal-like breast tumors." (PMID 26517092, 2015).
colon cancer (1 paper, 2020). "To extend our findings of BORA functions in other tumors, we silenced BORA in a subset of other cancer cell lines from prostate, endometrial, neuroblastoma and colon cancer." (PMID 32268485, 2020).
gastric adenocarcinoma (1 paper, 2020). "BORA, as the key intermediate protein of Aurora A and PLK1, was reported to be a potential biomarker for prognosis in lung, breast, and gastric adenocarcinomas." (PMID 32655322, 2020).
ovarian tumors (1 paper, 2020). "In addition to the described oncogenic functions of BORA and its prognostic value in ovarian tumors, our data also highlights BORA as a potential novel therapeutic target." (PMID 32268485, 2020).
cancer (7 papers, 2015 to 2024). A tumor composed of atypical neoplastic, often pleomorphic cells that invade other tissues. "In the pan-cancer cohort of the WG-505 dataset, OncodriveFML identified BORA and CHAF1B as putative driver genes from the mutations in their 3′ UTR regions." (PMID 27311963, 2016). "BORA activates the key mitotic PLK1 function as a prerequisite for mitotic entry and G2/M checkpoint recovery and high BORA correlates with increased cancer cell proliferation and high grade of chromosomal instability." (PMID 34065956, 2021). "In particular, our experimental approach unveils BORA as an oncogenic regulator in OC, which modulates multiple cancer related key processes and offers potential therapeutic avenues for the future, either by targeting BORA itself or its downstream effectors." (PMID 32268485, 2020). "In this regard, understanding the role of BORA in cancer cells will add valuable insights into BORA/PLK1-related mechanisms and might offer novel opportunities for therapeutic intervention in OC." (PMID 32268485, 2020). "Seven genes (BORA, DIS3, POLR2C, FAM175A, EME1, RNF139 and SHMT1) are considered potential biomarkers and/or potential targets for radiotherapy and chemotherapy, as well as cancer susceptibility, cancer progression and metastasis-related genes." (PMID 26517092, 2015). "Moreover, BORA has been recently shown to be upregulated in other tumor types and as a biomarker of radiation response in human lymphoblastoid cell lines, but little is known about the possible functional implication of BORA itself in cancer." (PMID 32268485, 2020). "We showed a reduction in key cancer related proteins: BCL2, CDK6, p65 and JNK1 kinase, suggesting that reduction of the expression of these proteins might contribute to the effects of BORA depletion on cell survival." (PMID 32268485, 2020). "Since Aurora-A is upregulated in certain cancer cell lines, which could influence the stoichiometry and function of the kinase:co-activator complexes, expression levels of these factors (i.e. Aurora-A, CEP192, TPX2, TACC3 and BORA) were determined across cell lines (Fig. EV1A)." (PMID 39327527, 2024).
tumor (5 papers, 2012 to 2020). "In agreement with the already established function of BORA in mitotic division, we also found a positive correlation of BORA levels with the proliferation marker Ki67, suggesting that expression of BORA labels highly proliferative tumor cells." (PMID 32268485, 2020). "Supported also by the fact that suppression of BORA levels in vivo impairs tumor progression, BORA silencing represents an advantage when aiming at specifically targeting malignant dividing cells." (PMID 32268485, 2020). "Our data pinpoint BORA as a prognostic biomarker and as an essential mediator of tumor cell proliferation and migration in OC." (PMID 32268485, 2020). "Together, constitutive BORA depletion in SK-OV-3-implanted mice, impacts on tumor engraftment, modulating tumor fate and thereby reducing tumor growth." (PMID 32268485, 2020). "Higher BORA mRNA expression was seen in tumor primary tissues compared to benign ovarian samples, and a significant correlation was observed with advanced stage." (PMID 32268485, 2020). "BORA-overexpressing cells also showed increased proliferation and higher capacity to form colonies in soft agar, thereby suggesting that high levels of BORA can contribute to tumor progression in transformed cells." (PMID 32268485, 2020). "We further analyzed the mRNA levels of BORA in 13 paired tumor-metastasis patient-samples (26 samples in total) and a significant upregulation of BORA was seen in metastasis compared to matched primary tumors, strengthening the notion that BORA levels correlate with OC aggressiveness." (PMID 32268485, 2020). "However, the expression of BORA and its effects on tumor biology are rarely reported especially in BCa." (PMID 32655322, 2020). "Meanwhile, ZNF300 might activate CDK1 through inhibition of WEE1 and MYT1 and modulation of the MYC/AURKA/BORA/PLK1 axis to promote the tumour cells to overcome G2 arrest and enter the M phase to avoid the apoptosis induced by chemotherapeutic drugs." (PMID 33078469, 2020). "Taken together, BORA clearly contributes to OC tumor growth in vivo." (PMID 32268485, 2020). "Among the genes significantly co-activated in G3 basal-like tumor samples, we identified 3 reproducible and concordantly up-regulated SAGPs (ABI1/PDSS1, DIS3/BORA and WDR77/ATP5F1)." (PMID 26517092, 2015). "The results showed that BORA was highly expressed in 404 tumor tissues compared to 28 normal tissues in bladder." (PMID 32655322, 2020). "Overexpression of BORA at protein level has been recently explored in several tumor types, but not yet in OC." (PMID 32268485, 2020).
adenocarcinoma (1 paper, 2026). A common cancer characterized by the presence of malignant glandular cells. "While BORA is not well characterized as a prognostic factor in GBM, protein aurora borealis (BORA) has been identified as a poor prognostic factor in adenocarcinoma." (PMID 41139700, 2026).
BORA also shares sentences with these, for which no sentence is quoted: breast carcinoma (1 paper); neuroblastoma (1).